CMIP (c-Maf inducing protein)
Diseases named in the same sentence as CMIP in open-access papers (continued):
Sharing a sentence is not in itself a finding about the gene and the disease.
Hodgkins lymphoma (1 paper, 2021). A heterogeneous group of malignant lymphoid neoplasms of B-cell origin characterized histologically by the presence of Hodgkin and Reed-Sternberg (HRS) cells in the vast majority of cases. "Paraneoplastic nephropathies strongly suggest that the CMIP protein expressed in Hodgkin lymphoma and in some solid tumors keeps an intact structure, function, and deleterious effect on glomeruli." (PMID 33917766, 2021).
Hypertension (1 paper, 2020). The presence of chronic increased pressure in the systemic arterial system. "Multiple linear regression analysis showed that serum TC was significantly associated with alanine aminotransferase (ALT), UA, CMIP rs16955379 with the C allele, hypertension, and drinking status." (PMID 33112407, 2020). "Serum LDL-C was associated with ALT, UA, CMIP rs16955379 with the C allele, and hypertension." (PMID 33112407, 2020).
lipid metabolism disorders (1 paper, 2022). "Previous studies suggested that CMIP was associated with lipid metabolism, and its rs16955379 variant was linked to lipid metabolism disorders, which might thus increase the risk of T2DM." (PMID 35073990, 2022).
major depressive disorder (1 paper, 2021). An episode of depression lasting two or more weeks without an intervening episode of mania. "A large scale GWAS study conducted by Gedik (2017) found that the SNP rs77700579 in CMIP was associated with major depressive disorder (MDD), supporting the conclusion that CMIP was a potential candidate gene for neuropsychiatric disorders." (PMID 34484985, 2021). "CMIP contributes to several biological pathways and is involved in various diseases such as glioma, gastric cancer, kidney disease, and dyslipidemia, as well as major depressive disorder, syndromic autism spectrum disorders, and specific language impairments." (PMID 34484985, 2021).
melanoma (1 paper, 2021). A malignant, usually aggressive tumor composed of atypical, neoplastic melanocytes. "Interestingly, in the context of melanoma, CMIP and its regulating lncRNA LINC00518 have been described as a two-gene signature to distinguish cancer from hyperpigmented nevi lesions." (PMID 33917766, 2021).
myopia (1 paper, 2022). "A previous study has suggested that CMIP is expressed in the nervous system and interacts with NF-κB, which is dysregulated in myopia." (PMID 36313450, 2022). "In addition, CMIP, C-Maf-inducing protein, was correlated with downregulation of the lncRNA XR_866459.4 in the context of myopia." (PMID 36313450, 2022).
nephrotic syndrome (1 paper, 2021). A collection of symptoms that include severe edema, proteinuria, and hypoalbuminemia; it is indicative of renal dysfunction. "Independently of a potential oncogenic role of CMIP in tumors, a collateral effect of its expression is the induction of nephrotic syndrome." (PMID 33917766, 2021). "CMIP expression has also been reported in several types of cancer, including blood malignancies and solid tumors, in many cases accompanied by nephrotic syndrome." (PMID 33917766, 2021).
polyarthritis (1 paper, 2018). "Three patients with class II biopsy exhibiting high CMIP abundance in podocytes responded promptly to steroid therapy alone (prednisone, 1mg/kg), which was initiated because of extrarenal manifestations including neurolupus (one case) and severe polyarthritis (two cases)." (PMID 30439969, 2018).
schizophrenia (1 paper, 2021). A major psychotic disorder characterized by abnormalities in the perception or expression of reality. "This study identified a potential CMIP variant that may confer schizophrenia risk in the female Han Chinese population." (PMID 34484985, 2021). "In this study, we evaluated the genetic association between the C-Maf-inducing protein (CMIP) gene and schizophrenia in the Han Chinese population." (PMID 34484985, 2021). "The in-depth link between CMIP and schizophrenia was explored through linkage disequilibrium (LD) and further haplotype analyses." (PMID 34484985, 2021).
Wilms tumour (1 paper, 2020). "An additional study found that the Wilms tumour suppressor gene may protect podocytes by binding to the CMIP promoter in vivo and repressing its transcription." (PMID 33112407, 2020).
cancer (8 papers, 2015 to 2024). A tumor composed of atypical neoplastic, often pleomorphic cells that invade other tissues. "A different perspective associates CMIP and cancer, as its expression is specifically increased in podocytes from patients treated with receptor tyrosine kinase inhibitors (RTKI)." (PMID 33917766, 2021). "CMIP is an undeniable target in paraneoplastic syndromes, and a risk factor of renal toxicity in anti-cancer therapies." (PMID 33917766, 2021). "c-Mip (C-maf inducing protein) is an 86 KDa protein with unclear functions that is upregulated in the podocytes of patients with NS in association with conditions such as cancer that predispose the development of NS." (PMID 37503337, 2023). "This complementary counterbalance of both proteins is a relevant element in CMIP function, in its relation to cancer and is developed below." (PMID 33917766, 2021). "The ensemble of these reports strongly suggests a dual scenario for CMIP in cancer and normal cells." (PMID 33917766, 2021). "As a consequence, a growing body of evidence points at CMIP as playing a role in cancer." (PMID 33917766, 2021). "Is CMIP expression part of a counter-regulatory mechanism in cancer cells?" (PMID 33917766, 2021). "Therefore, CMIP has been reported as holding a proapoptotic function in non-cancer cells by two independent laboratories." (PMID 33917766, 2021). "In addition to these observations, a growing body of evidence suggests a close functional link between CMIP and cancer." (PMID 33917766, 2021). "In particular, interactions with RelA, PI3K, and Dip1 place CMIP at the functional crossroads of survival/death pathways, which may be decisive in cell fate, and impact differently normal and cancer cells." (PMID 33917766, 2021). "The methylation status of the CMIP promoter, on the contrary, could be modified in cancer cells." (PMID 33917766, 2021). "However, is there a case for CMIP constituting a target in anti-cancer therapy?" (PMID 33917766, 2021). "C-Maf inducing protein (CMIP) has oncogenic properties and is expressed in a variety of malignant tumors." (PMID 38978060, 2024).
tumor (5 papers, 2017 to 2022). "One possibility is that CMIP sequence is mutated in tumor cells—like tumor suppressors such as WT1 in some malignancies-." (PMID 33917766, 2021). "CMIP showed anti-metastasis activity by reducing the amount of tumor nodules in the lung of tumor-bearing mice and extended their lives on a mouse model of 4T1 breast cancer lung metastasis." (PMID 35893547, 2022). "CMIP has been defined by independent groups as either tumor suppressor—because of its proapoptotic effects—and as oncogenic." (PMID 33917766, 2021). "If CMIP is repressed by transcription factors that are generally upregulated in tumor cells, such as NF-κB, there must be an alternative mechanism leading to its upregulation." (PMID 33917766, 2021). "A new anti-tumor protein was separated from the seed entity of C. militaris, named CMIP." (PMID 35893547, 2022). "Assuming that CMIP exerts pro-apoptotic effects in normal cells, and basically inhibits pro-survival pathways and cell proliferation, why is this proapoptotic protein expressed in tumor cells?" (PMID 33917766, 2021). "However, thus far, there is no publication that documents the relation between CMIP and human tumor behaviors." (PMID 28744466, 2017).
kidney disease (3 papers, 2018 to 2020). "In addition, one study showed that CMIP is associated with kidney disease, especially podocyte-related kidney disease." (PMID 33112407, 2020). "Some scholars have reported that CMIP may affect cholesterol excretion, causing abnormal lipid metabolism in patients with kidney disease." (PMID 33112407, 2020). "In two cases (one class II and one class III) displaying a high nuclear abundance of CMIP in podocytes, the control of renal disease required intravenous cyclophosphamide in addition to steroid therapy with a favorable outcome." (PMID 30439969, 2018).
CMIP also shares sentences with these, for which no sentence is quoted: minimal change nephropathy (2 papers); attention deficit-hyperactivity disorder (1); Chagas disease (1); endometrial cancer (1); endometriosis (1); Intellectual disability (1); metabolic disease (1); metabolic dysfunction-associated steatotic liver disease (1); metabolic syndrome (1); Nephropathy (1); ovarian carcinoma (1); specific language impairment (1).